DNAH8 (dynein axonemal heavy chain 8)
Description:
Force generating protein component of the outer dynein arms (ODAs) in the sperm flagellum. Produces force towards the minus ends of microtubules. Key component of dynein, a family of motor proteins essential for movement along microtubules (By similarity). Dynein has ATPase activity; the force-producing power stroke is thought to occur on release of ADP. Involved in sperm motility; implicated in sperm flagellar assembly.
Synonyms: hdhc9; ATPase; SPGF46
Tractability: No criterion of Open Targets' tractability assessment is met for any kind of drug.
Gene: Protein-coding gene on chromosome 6 (38,715,311 to 39,030,792, forward strand). Ensembl gene ENSG00000124721.
Subcellular location: Cytoplasm, cytoskeleton, flagellum axoneme; Cytoplasm
Subcellular location (Human Protein Atlas): Mid piece; Principal piece
Gene Ontology:
Molecular function: microtubule motor activity; dynein intermediate chain binding; dynein light intermediate chain binding; minus-end-directed microtubule motor activity; ATP binding
Biological process: cilium movement involved in cell motility; cilium-dependent cell motility; outer dynein arm assembly; microtubule-based movement
Cellular component: axoneme; sperm flagellum; sperm midpiece; sperm principal piece; axonemal dynein complex; cytoplasm; outer dynein arm; 9+2 motile cilium; dynein complex
Genetic constraint (gnomAD): Loss-of-function variants: 222 observed, 358.69 expected, observed/expected ratio (o/e) 0.62, 90% interval 0.55 to 0.69. The upper end of that interval is the gene's LOEUF score, 0.69, which puts it in group 2 of 6, group 1 being the genes least tolerant of losing a copy. Missense variants: 3,817 observed, 4,293.9 expected, observed/expected ratio (o/e) 0.89, 90% interval 0.87 to 0.91. Synonymous variants: 1,417 observed, 1,492.9 expected, observed/expected ratio (o/e) 0.95, 90% interval 0.91 to 0.99.
Gene-disease validity (ClinGen):
ClinGen rates the evidence that DNAH8 causes each of these diseases.
spermatogenic failure 46 (autosomal recessive): Strong.
primary ciliary dyskinesia (autosomal recessive): Disputed. A rare, genetically heterogeneous, primarily respiratory disorder characterized by chronic upper and lower respiratory tract disease.
Homologues: Orthologues: chimpanzee DNAH8 (99% identical), macaque DNAH8 (98% identical), guinea pig DNAH8 (93% identical), pig DNAH8 (92% identical), rat Dnah8 (92% identical), mouse Dnah8 (92% identical), dog DNAH8 (91% identical), rabbit DNAH8 (90% identical), zebrafish dnah5l (56% identical), Drosophila melanogaster Dhc1 (52% identical). Paralogues in human: DNAH5 (60% identical), DNAH10 (29% identical), DNAH2 (28% identical), DNAH9 (28% identical), DNAH17 (28% identical), DNAH11 (27% identical), DNAH1 (27% identical), DNAH3 (25% identical), DNAH7 (25% identical), DNAH6 (25% identical), DNAH12 (25% identical), DNAH14 (22% identical), and 3 more.
Diseases named in the same sentence as DNAH8 in open-access papers:
DNAH8 is named in the same sentence as 287 diseases in open-access papers, as found by Europe PMC text mining. Sharing a sentence is not in itself a finding about the gene and the disease. The quoted sentences say what the papers report.
prostate carcinoma (18 papers, 2008 to 2025). A carcinoma that arises from epithelial cells of the prostate gland. "The main function of DNAH8 is currently understood to be related to sperm motility and has been shown to be a marker for poor prognosis in prostate cancer and to be associated with metastasis." (PMID 36831619, 2023). "In cancer, DNAH8 was proposed to be associated with the prognosis of prostate cancer and hepatocellular carcinoma." (PMID 36319832, 2022). "DNAH8 has been reported to be a novel regulator of the androgen receptor that is associated with metastatic tumors and poor prognosis in patients with prostate cancer." (PMID 30944005, 2019). "This indicates a strong and specific association between DNAH8 mRNA expression and prostate cancer progression." (PMID 27363033, 2016). "The strong association between DNAH8 and human prostate cancer prompted us to further investigate its expression in normal human tissues." (PMID 27363033, 2016). "Consistent with a role for DNAH8 in promoting AR activity and prostate cancer progression, DNAH8 resided in a cancer-associated amplicon, and contained a coding SNP in prostate cancer." (PMID 27363033, 2016). "To examine if DNAH8 expression coincides with AR activity in prostate cancer patients, we took a meta-analysis approach and examined the mRNA expression patterns of DNAH8 and PSA as a surrogate for active AR signaling." (PMID 27363033, 2016). "Using prostate cancer cell models, we investigated the regulation and crosstalk between AR and DNAH8." (PMID 27363033, 2016). "To explore DNAH8 function in prostate cancer and its regulatory effect on the AR pathway, we examined DNAH8 protein expression from eight patient-derived prostate cancer cell lines." (PMID 27363033, 2016). "Depletion of DNAH8 in prostate cancer cells suppressed AR transcriptional activity and proliferation." (PMID 27363033, 2016). "This suggests that factors in addition to DNAH8 regulate AR-mediated gene expression during prostate cancer initiation and progression, and is consistent with multiple AR regulatory factors being identified in our RNAi screen." (PMID 27363033, 2016). "Further studies on the mechanism of DNAH8-mediated AR activity will be required to elucidate the role DNAH8 plays in promoting ligand-independent AR activation in prostate cancer." (PMID 27363033, 2016). "Therefore, DNAH8 affects both androgen-dependent and -independent prostate cancer cell proliferation, in part by controlling AR activity." (PMID 27363033, 2016). "Thus, our integrated analysis revealed DNAH8 as a putative high-priority therapeutic target and prognostic indicator in prostate cancer." (PMID 27363033, 2016). "DNAH8 was also positively associated with NKX3.1 (correlation coefficient 0.15, upper limit 0.23, lower limit 0.08, and p < 0.05) and FKBP5 (correlation coefficient 0.08, upper limit 0.15, lower limit 0.01, and p < 0.05) expression in prostate cancer." (PMID 27363033, 2016). "This further supports a link between DNAH8 and prostate cancer." (PMID 27363033, 2016). "Here we report that DNAH8 functions in prostate cancer and affects AR signaling." (PMID 27363033, 2016). "It is possible that upon increased DNAH8 expression during prostate cancer progression, DNAH8 could increase AR and/or AR cofactor nuclear accumulation and foster androgen-independent AR activation." (PMID 27363033, 2016). "However, the expression of DNAH8 was undetectable in five different prostate cancer cell lines." (PMID 34696780, 2021). "Therefore, DNAH8 copy number amplification, in concert with or independent of AR, could promote DNAH8 expression in advanced prostate cancer." (PMID 27363033, 2016). "To determine the potential relevance of DNAH8 and DNAH5 in human prostate cancer, we examined for differences in mRNA expression among normal, primary and metastatic samples from independent validation cohorts containing 235 normal prostate, 329 primary tumor and 59 metastatic tumor cases." (PMID 27363033, 2016).
prostate carcinoma (continued). "Whereas DNAH8 protein abundance appeared higher in AR-expressing compared to non-AR-expressing prostate cancer cells lines, this paralleled androgen-dependent DNAH8 mRNA expression and AR recruitment to the DNAH8 promoter." (PMID 27363033, 2016). "Axonemal dyneins function in cellular motility, but the function of DNAH8 in prostate cancer or other cell types has not been reported." (PMID 27363033, 2016).
male infertility (11 papers, 2020 to 2025). The inability of the male to effect fertilization of an ovum after a specified period of unprotected intercourse. "Among them, genes co-location with lncRNA Dnah8 and lncRNA Topaz1 were associated with male infertility." (PMID 40577378, 2025). "It has been reported that DNAH8 variants lead to morphological abnormalities in the sperm flagella and male infertility." (PMID 36834539, 2023). "Loss-of-function mutation in DNAH8 is suggested to cause male infertility because of the multiple morphological abnormalities of sperm flagella syndrome, DNAH8 being essential for sperm flagellum formation." (PMID 34336830, 2021). "DNAH8 had first been linked to male infertility, but was also described in a patient with PCD." (PMID 37998386, 2023). "For example, mutations in IDA and ODA genes, such as DNAH1, DNAH2, DNAH8, and DNAH10, cause male infertility due to asthenozoospermia with multiple morphological abnormalities of the sperm flagella." (PMID 36726469, 2022). "Additionally, other DNAHs, such as DNAH1, DNAH2, DNAH8, DNAH10, DNAH12, and DNAH17, are suggested to be pathogenic genes of isolated male infertility." (PMID 39503742, 2024). "Mutations in two IDA heavy-chain protein-encoding genes, DNAH1 (MIM: 603332) and DNAH2 (MIM: 603333), and two ODA heavy chain components, DNAH8 (MIM: 603337) and DNAH17 (MIM: 610063), have been described in individuals with isolated male infertility due to asthenoteratozoospermia." (PMID 37424858, 2023).
cardiomyopathy (9 papers, 2013 to 2026). A disease of the heart muscle or myocardium proper. "However, DNAH17 and DNAH8 mutations have been clinically implicated in spermatogenic failure [OMIM: 618643] and have never been reported in association with cardiomyopathy." (PMID 34387706, 2021).
infertile (6 papers, 2013 to 2024). "It has been demonstrated that infertile males with variants in DNAH1, DNAH2, DNAH7, and DNAH8 have a favorable prognosis, while patients with variants in DNAH17 have poor outcomes after ICSI treatment." (PMID 39503742, 2024). "Analysis of additional subjects is needed to understand genetic variants in genes such as DNAH8 that are linked to infertility, and current data are not clear about their role in the respiratory motile cilia." (PMID 35626283, 2022).
autoimmune disease (5 papers, 2015 to 2025). A disorder resulting from loss of function or tissue destruction of an organ or multiple organs, arising from humoral or cellular immune responses of the individual to their own tissue constituents. "The relationship between GMPR, DNAH8, MCEMP1, and autoimmune diseases has not yet been reported." (PMID 38639399, 2024).
metastatic disease (2 papers, 2016 to 2019). "Thus, DNAH8 is a new regulator of AR associated with metastatic tumors and poor prognosis." (PMID 27363033, 2016). "We also found that the DNAH8 gene is amplified in metastatic prostate cancer (data not shown), consistent with elevated DNAH8 mRNA expression in metastatic disease." (PMID 27363033, 2016).
bipolar disorder (1 paper, 2023). A disorder of the brain that causes unusual shifts in mood, energy, activity levels and the ability to carry out day-to-day tasks. "In contrast, bipolar disorder, which was significant in the UK GWAS dataset, was also significantly present in the merged set by adding two novel genes from the Japanese GWAS: DNAH8 (chr6:38,681,087-39,000,568) and IMPA1 (chr8:82,567,151-82,600,589)." (PMID 36902448, 2023).
hypospadias (1 paper, 2025). Hypospadias is the displacement of the urethral meatus on the ventrum of the penis. "In our previous study, a novel risk gene for hypospadias, DNAH8, was discovered through large-scale WES." (PMID 41463044, 2025). "Our results provide convincing evidence that DNAH8 is a risk gene for hypospadias, characterize its function, and offer new strategies for the prevention and treatment of hypospadias." (PMID 41463044, 2025). "Through whole-exome sequencing, we found that rare damaging variants in DNAH8 (dynein axonemal heavy chain 8) were significantly enriched in hypospadias cases." (PMID 41463044, 2025). "Further research such as generating patient-specific point mutation knock-in mice models is needed to strengthen our findings and determine whether human DNAH8 variants recapitulate hypospadias phenotypes." (PMID 41463044, 2025). "This study emphasized that DNAH8 is a risk gene of hypospadias, presented supplementing evidence of the function of cilia genes and provided a stable and reliable hypospadias susceptibility animal model for future studies on the interaction between genetic factors and EDCs." (PMID 41463044, 2025). "However, the role of DNAH8 deficiency in hypospadias pathogenesis remains unclear." (PMID 41463044, 2025). "Here, we established a DNAH8 knockout mouse model and verified the effect of the variation on the development of hypospadias and abnormal masculinization." (PMID 41463044, 2025). "Therefore, we chose a lower dose that is more realistic, and the results showed that the synergistic effect of DNAH8 deficiency and low-dose DEHP can lead to hypospadias, and the DNAH8 KO mouse is an ideal genetic susceptibility model of hypospadias." (PMID 41463044, 2025). "There were no observed phenotypes of hypospadias or reduced penile development, which was consistent with previous studies showing that male mice heterozygous or homozygous for the DNAH8, DNAH9, and DNAH17 pathogenic mutations did not have the hypospadias phenotype." (PMID 41463044, 2025). "Furthermore, DNAH8 knockout could synergistically interact with low-dose endocrine-disrupting chemicals, increasing the incidence of urethral fusion defects at E16.5, and led to clear hypospadias phenotypes at E18.5." (PMID 41463044, 2025). "However, in DNAH8 knockout mice, low-dose DEHP markedly increased the incidence of urethral fusion defects at E16.5 and led to clear hypospadias phenotypes at E18.5." (PMID 41463044, 2025).
meningioma (1 paper, 2020). A generally slow growing tumor attached to the dura mater. "Six potentially pathogenic mutations in PHRF1, ZC3H12B, H2AFV, DNAJC13, DNAH8, SCN2A were non-recurrent; however, given the modest sample size it is difficult to fully evaluate the importance of these variants in the meningioma progression." (PMID 32724039, 2020).
metastatic prostate carcinoma (1 paper, 2016). A carcinoma that arises from the prostate gland and has spread to other anatomic sites. "Using this approach, we discovered Dynein Axonemal Heavy Chain 8 (DNAH8) as an AR regulatory factor that is overexpressed in metastatic prostate cancer and predictive of poor prognosis." (PMID 27363033, 2016). "It should be noted that the mRNA expression of DNAH8 and AR were not significantly correlated in the metastatic prostate cancer cases (p = 0.45." (PMID 27363033, 2016).
tumor (124 papers, 2006 to 2025). "Malignant lesions had dramatically increased DNAH8 staining when compared with adjacent normal prostate tissue, further suggesting an association of DNAH8 with tumor development and progression that is consistent with the mRNA expression analysis." (PMID 27363033, 2016). "Somatic mutations enriched in the low-risk group (e.g., CDKN2A, MUC16, DNAH8) may reflect increased neoantigen load, enhancing tumor visibility to the immune system." (PMID 40909289, 2025). "We next used retrospective analysis to determine whether DNAH8 expression was associated with tumor recurrence after androgen deprivation." (PMID 27363033, 2016). "QRT-PCR showed that the expression of the ACTA2, C1QTNF9, DNAH8, GATM, LBP, and NGF were significantly downregulated in tumor samples." (PMID 36319832, 2022). "It is interesting that DNAH8, but not PSA mRNA expression in primary tumors was associated with tumor recurrence." (PMID 27363033, 2016).
prostate (1 paper, 2016). "Consistent with this idea, meta-analysis revealed that DNAH8 and AR-target gene expression were positively associated in prostate caner." (PMID 27363033, 2016).
DNAH8 also shares sentences with these, for which no sentence is quoted: cancer (196 papers); infection (64); breast carcinoma (29); lung carcinoma (12); melanoma (12); colon carcinoma (10); diabetes (10); viral infection (10); colorectal cancer (9); ischemia (9); Parkinson disease (9); Alzheimer disease (8); glioma (8); heart failure (8); neurodegenerative disease (8); non-small cell lung carcinoma (8); ovarian carcinoma (8); bacterial infection (7); leukemia (7); neurological disorders (7); acute myeloid leukemia (6); amyotrophic lateral sclerosis (6); Fanconi anemia (6); Hypertension (6); neuropathies (6); pancreatic cancer (6); Sepsis (6); type 2 diabetes (6); bladder cancer (5); epilepsy (5).
A further 245 diseases each share a sentence with DNAH8 in 5 papers or fewer.